MBL2 (mannose binding lectin 2)
Description:
Calcium-dependent lectin, which acts as a pattern recognition receptor that initiates the lectin pathway of the complement system, a cascade of proteins that leads to phagocytosis and breakdown of pathogens and signaling that strengthens the adaptive immune system. Specifically recognizes and binds the mannose moiety of carbohydrates on the pathogen surface, activating the MASP1 serine protease and initiating the proteolytic cascade of the lectin complement pathway. Upon SARS coronavirus-2/SARS-CoV-2 infection, activates the complement lectin pathway which leads to the inhibition SARS-CoV-2 infection and a reduction of the induced inflammatory response. May bind DNA.
Synonyms: MBP-C; COLEC1; MBL; MBP1; MBP; HSMBPC; MBL2D; MBPD
Tractability: Antibody: UniProt places it where antibodies can reach, with high confidence; its Gene Ontology location is reachable by antibodies, with high confidence; UniProt predicts a signal peptide or a membrane-spanning region. PROTAC: its protein half-life has been measured.
Gene: Protein-coding gene on chromosome 10 (52,765,377 to 52,772,784, reverse strand). Ensembl gene ENSG00000165471.
Subcellular location: Secreted; Cell surface
Pathways (Reactome):
Disease: Dengue virus activates/modulates innate and adaptive immune responses; SARS-CoV-2 activates/modulates innate and adaptive immune responses
Immune System: Initial triggering of complement; Lectin pathway of complement activation
Gene Ontology:
Molecular function: calcium-dependent protein binding; D-mannose binding; identical protein binding; pattern recognition receptor activity; protein binding; signaling receptor binding
Biological process: antiviral innate immune response; cell surface pattern recognition receptor signaling pathway; complement activation, lectin pathway; defense response to Gram-positive bacterium; innate immune response; negative regulation of viral process; positive regulation of opsonization; proteolysis; acute-phase response; defense response to bacterium; opsonization; positive regulation of phagocytosis; response to oxidative stress; surfactant homeostasis
Cellular component: cell surface; extracellular region; serine-type endopeptidase complex; symbiont cell surface; external side of plasma membrane; multivesicular body
Genetic constraint (gnomAD): Loss-of-function variants: 5 observed, 6.87 expected, observed/expected ratio (o/e) 0.73, 90% interval 0.38 to 1.5. That is too few expected variants to judge how well the gene tolerates losing a copy. Missense variants: 277 observed, 256.24 expected, observed/expected ratio (o/e) 1.08, 90% interval 0.98 to 1.19. Synonymous variants: 105 observed, 98.51 expected, observed/expected ratio (o/e) 1.07, 90% interval 0.91 to 1.25.
Homologues: Orthologues: chimpanzee MBL2 (98% identical), macaque MBL2 (90% identical), rabbit MBL2 (67% identical), guinea pig MBL2 (66% identical), pig MBL2 (64% identical), rat AABR07006691.1 (60% identical), mouse Mbl2 (59% identical), tropical clawed frog mbl2 (45% identical), zebrafish mbl2 (37% identical), zebrafish hbl1 (37% identical), zebrafish hbl4 (37% identical), zebrafish hbl2 (36% identical), and 1 more.
Diseases named in the same sentence as MBL2 in open-access papers:
MBL2 is named in the same sentence as 274 diseases in open-access papers, as found by Europe PMC text mining. Sharing a sentence is not in itself a finding about the gene and the disease. The quoted sentences say what the papers report.
COVID-19 (30 papers, 2020 to 2025). A disease caused by infection with severe acute respiratory syndrome coronavirus 2. "Neither the combinations of the short haplotypes nor distribution of the exonic single wildtype and variant alleles of MBL2 were associated with COVID-19." (PMID 37051252, 2023). "It has been demonstrated that the MBL2 gene B variant at codon 54 (rs1800450) is associated with variabilities in the clinical course of COVID-19." (PMID 36836739, 2023). "The present study evaluated the frequency of exon 1 polymorphisms of the MBL2 gene in patients with severe COVID-19 and patients with long COVID." (PMID 37138871, 2023). "We therefore aimed to investigate the role of lectin pathway activation in COVID-19 in two independent patient cohorts, while also looking at the six most common polymorphisms found in the MBL2 gene." (PMID 37051252, 2023). "It has been demonstrated that the mannose-binding lectin 2 gene B variant at codon 54 (rs1800450) is associated with variabilities in the clinical course of COVID-19." (PMID 36836739, 2023). "Based on the previous evidence of association between MBL2 genetic polymorphisms and COVID-19 severity, we investigated a potential correlation between MBL deficiency, or low MBL levels, and the development of brain fog after COVID-19." (PMID 37398656, 2023). "The MBL2 B allele was demonstrated to be a risk factor for severe COVID-19 in some previous studies, and hence MBL2 gene variants are thought to play a very important role in COVID-19 susceptibility and disease severity." (PMID 36836739, 2023). "The frequencies of the polymorphic MBL2 genotype (OO) and allele (O) were higher in patients with severe COVID-19 (p< 0.05)." (PMID 37138871, 2023). "The present study investigated the association of MBL2 genotypes with the severity of acute COVID-19 and long COVID." (PMID 37138871, 2023). "This systematic review and meta-analysis will summarize the association of IFNL4, ACE1, PKR, IFNG, MBL2 genetic polymorphisms, and severe COVID-19." (PMID 35623072, 2022). "Instead, low MBL2 serum levels and avariant of the gene MBL2 were pointed out as risk factors forSARS-CoV-1 infection that causes the COVID-19-related disease SARS." (PMID 34436508, 2021). "Interestingly, MBL2, a protein involved in complement activation, has been previously associated with COVID-19 severity and mortality in intensive care patients." (PMID 38565620, 2024). "Mannan-binding lectin (MBL), the first recognition subcomponent of the C lectin pathway, has been shown to bind to glycosylated SARS-CoV-2 spike protein, genetic variants of MBL2 are suggested to have an association with severe COVID-19 manifestations requiring hospitalization." (PMID 37398656, 2023). "We therefore investigated activation of the lectin pathway in two independent cohorts of SARS-CoV-2 infected patients, while also analysing MBL protein levels and potential effects of the six major single nucleotide polymorphisms (SNPs) found in the MBL2 gene on COVID-19 severity and outcome." (PMID 37051252, 2023). "These are characteristic manifestations of the severe form of COVID-19, which suggests that polymorphisms in the MBL2 gene that lead to MBL deficiency may significantly contribute to the systemic dysregulation of the organism." (PMID 37138871, 2023). "These clusters include only a few members of the complement pathway: C6C9Serpin A1 and G1and MBL2 (Mannose-binding lectin 2) a pattern recognition molecule that initiates the lectin pathway of complement activationwith polymorphisms associated with COVID-19 severity." (PMID 36348270, 2022). "In addition, also the wildtype MBL2 A alleles (A/A) were associated with a lower risk of dying from COVID-19, while individuals bearing the B/B combination seem to be at a higher risk to die from COVID-19." (PMID 37051252, 2023). "Frequencies of short MBL2 haplotype combinations in healthy controls and cases (merged COVID-19 cohorts (CAM+BUD)." (PMID 37051252, 2023).
COVID-19 (continued). "This study investigated the association of MBL2 gene polymorphisms with the plasma levels of MBL and inflammatory cytokines in COVID-19." (PMID 37138871, 2023). "Since activation of the lectin pathway is highly dependent on its key pattern recognition molecule MBL, genotyping of the MBL2 gene was performed for both COVID-19 cohorts as well as for the healthy controls." (PMID 37051252, 2023). "This study will systematically evaluate the impact of IFNL4, ACE1, PKR, IFNG, and MBL2 in the course of severe COVID-19 using electronic databases and paper-based literature with an eye to the current genetic profile of the severe COVID-19 population." (PMID 35623072, 2022). "This study aims to perform a systematic evaluation and meta-analysis of the effects of IFNL4, ACE1, PKR, IFNG, and MBL2 in the course of severe COVID-19." (PMID 35623072, 2022). "While anti-SARS-CoV-2 antibody levels were similar in COVID-19 ICU patients who survived and died, MBL2 and PTX3 were associated with poor outcome pointing towards the importance of antibody-independent mechanisms of complement activation in COVID-19." (PMID 34099652, 2021). "Our proteomics data reveal that complement activation is a core component of the overreaction of the immune system in response to COVID-19, with elevated MBL2 being a predictor of 28-day ICU mortality." (PMID 34099652, 2021). "Previous studies demonstrated association of MBL plasma levels with acute COVID-19 MBL2 gene polymorphisms, where patients with polymorphic genotypes had lower levels of MBL, but these assessments were made only in patients with severe COVID-19 forms." (PMID 37138871, 2023). "Evaluation of the frequencies of polymorphisms in the MBL2 gene between patients with severe and non-severe manifestations of acute COVID-19." (PMID 37138871, 2023). "Some studies that evaluated polymorphisms in the MBL2 gene in groups of patients with severe and non-severe clinical forms of COVID-19 observed association of variant B (rs1800450) with the severity of the disease." (PMID 37138871, 2023). "Interestingly, genetic polymorphisms at the MBL2 locus have previously been associated with susceptibility to SARS-CoV-2 infection, and more recently, with COVID-19 severity." (PMID 37398656, 2023). "The MBL2 variant rs5030737 is positively correlated with the number of COVID-19 cases but not with the number of deaths." (PMID 35165525, 2022). "MBL2 levels were markedly elevated in COVID-19 ICU patients who died." (PMID 34099652, 2021). "The MBL2 (mannose-binding lectin) levelwas increased only in the COVID-19 group." (PMID 34436508, 2021). "Furthermore, we found MASP1, the downstream mediator of MBL2, to be increased in plasma from COVID-19 ICU patients compared with sepsis patients." (PMID 34099652, 2021). "Besides that, the MBL2 genotype does not greatly affect susceptibility to SARS-CoV-2 infections or disease outcomes such as COVID-19 related mortality and the development of Long COVID." (PMID 37051252, 2023). "The results suggest that, besides MBL2 polymorphisms promoting a reduction in MBL levels and therefore in its function, they may also contribute to the development of a more intense inflammatory process responsible for the severity of COVID-19." (PMID 37138871, 2023). "We observed an increase in the levels of several complement proteinsmost of which are exclusively induced in severe COVID-19 patientswhile upregulation of the lectin receptor MBL2 was also detected in COVID-19 non-ICU patients and further increased in COVID-19 ICU/F." (PMID 36348270, 2022). "However, the effects of IFNL4, ACE1, PKR, IFNG, and MBL2 in severe COVID-19 have not been systematically assessed." (PMID 35623072, 2022).
Sepsis (26 papers, 2009 to 2025). Sepsis is defined as life-threatening organ dysfunction caused by a dysregulated host response to infection. "MBL2 (odds ratio [OR] = 1.046) was a risk factor for sepsis, while the other proteins (FCER2: OR = 0.922; GZMB: OR = 0.908; CFHR5: OR = 0.858; HLA-DQA2: OR = 0.896; MPO: OR = 0.875) were safety factors." (PMID 39252215, 2024). "The overall results showed a significant association between MBL2 A/O and the risk of sepsis (OR = 1.25, 95% CI = 1.05–1.48, P = 0.01 for the dominant model; OR = 1.19, 95% CI = 1.04–1.36, P = 0.01 for the allelic model)." (PMID 30683156, 2019). "The aim of this study was to confirm or refute an association between common MBL2 genetic variants and sepsis susceptibility or outcome." (PMID 25969530, 2015). "We use a large cohort of immune competent adults to analyze the influence of MBL2 genetic variants on sepsis susceptibility and survival." (PMID 25969530, 2015). "The effect of MBL2 functional genetic variants has been studied extensively in a number of sepsis related phenotypes." (PMID 25969530, 2015). "MBL2 is one of the most extensively studied but still controversial candidate genes reported to be associated with sepsis and infectious disease phenotypes." (PMID 25969530, 2015). "We report a large, comprehensive analysis of associations between the most extensively studied functional MBL2 polymorphisms and sepsis survival, as well as susceptibility to CAP and pneumococcal pneumonia." (PMID 25969530, 2015). "Low MBL levels have been associated with increased risk of infection in adult populations, and there is an association of MBL2 gene mutations with increased mortality and sepsis." (PMID 25309541, 2014). "It was previously reported that two MBL2 polymorphisms (MBL-2 exon 1 and promoter -221) were associated with the development of sepsis, severe sepsis, and septic shock in Caucasian adults." (PMID 19891773, 2009). "• Homozygosity for the MBL2 structural genotype (A/A) and the -550 genotype (H/H) was associated with the progression from severe sepsis to septic shock." (PMID 19891773, 2009). "Additionally in a multicenter prospective study involving eight adults ICUs in U. K., the association between MBL-2 exon and promoter polymorphisms with the outcome of 174 patients affected by severe sepsis and septic shock was studied." (PMID 24223476, 2013). "Another recent Korean study in ICU patients investigated whether MBL2 gene polymorphisms and serum levels might influence severity and prognosis of sepsis." (PMID 24223476, 2013). "However, homozygosity for the MBL2 structural genotype (A/A) and the -550 genotype (H/H) was associated with the progression from severe sepsis to septic shock." (PMID 19891773, 2009). "We investigated whether polymorphisms in the MBL2 gene and the serum level are associated with the severity and prognosis of sepsis." (PMID 19891773, 2009). "By revealing a causal link between sepsis and CFHR5, FCER2, GZMB, HLA-DQA2, MBL2, or MPO, our study offers an essential resource for additional investigations on the subject." (PMID 39252215, 2024). "Primary outcome was the effect of genotype-based MBL2 levels on blood-culture proven and clinical sepsis during primary stay in hospital." (PMID 28558032, 2017). "Nevertheless, our findings strongly suggest that a clinically relevant relationship between MBL2 genotype and sepsis mortality in immune competent adults is highly unlikely." (PMID 25969530, 2015). "Our findings do not exclude the possibility that MBL2 functional polymorphisms significantly influence sepsis susceptibility and outcome in these patient groups." (PMID 25969530, 2015). "In this study, we investigated the relation between polymorphisms in MBL2 and the serum concentration of MBL, and assessed whether these polymorphisms influence the severity and prognosis of sepsis in a Korean population." (PMID 19891773, 2009).
Sepsis (continued). "This redundancy could explain the lack of a significant association between MBL2 functional polymorphisms and sepsis susceptibility and outcome in the present study of immune competent adults." (PMID 25969530, 2015). "Numerous studies have addressed MBL2 genotypes and/or serum MBL concentrations in relation to perinatal infections, including sepsis." (PMID 39464884, 2024). "A study on intensive care patients could not find any difference in frequency of MBL2-polymorfism between patients and controls at baseline, and between patients classified as having sepsis or not." (PMID 32817747, 2020).
viral infection (25 papers, 2011 to 2025). "Moreover, fetal MBL2 haplotypes and in utero exposure to viral infection increases the risk of preterm birth." (PMID 31253109, 2019). "There was only one case of viral infection in each group; in the MBL2 variant group this was caused by CMV, a potentially very serious disease, while the virus in the MBL2 wild-type group was a reactivation of varicella zoster, which is more common in hematological patients." (PMID 24886325, 2014). "There has also been interest to determine whether MBL2 polymorphisms can influence rates of viral infections related to cancer, including human papillomavirus (HPV) infection, hepatitis C virus and BK virus coinfection in HPV-positive cervical lesions." (PMID 23637788, 2013). "Single nucleotide polymorphisms of the MBL2, FCN and CD209 genes with associations with virus infections." (PMID 25642836, 2015). "Host genetic factors such as MBL2 gene polymorphisms cause defects in the polymerization of MBL protein and result in a functional deficiency and/or in low serum levels that can influence susceptibility to various viral infections." (PMID 30482213, 2018). "Although MBL2 haplotypes associated with deficiency appear to be a risk factor for a range of infections in neonates or other immune compromised patients, our study adds to the literature that carriage of low-producing MBL2 variants does not increase risk of severe viral infections." (PMID 31139182, 2019). "Finally, CCR7, MBL2, and MCOLN2 have all been connected to the modulation of host cellular and immune responses in viral infection." (PMID 33705408, 2021). "Not only that MBL2 polymorphisms and serum MBL deficiency have been found to be associated with susceptibility to bacterial and viral diseases, they have also been linked to non-communicable diseases such as cystic fibrosis, and COPD." (PMID 26684757, 2015). "In summary, our results would suggest that low pre-transplant MBL levels, but not MBL2 genotype, could predispose patients undergoing Allo-HSCT to have the first episode of infection earlier and to increase the risk of viral infection." (PMID 31706269, 2019).